SPC25 (SPC25 component of NDC80 kinetochore complex)
Diseases named in the same sentence as SPC25 in open-access papers (continued):
Sharing a sentence is not in itself a finding about the gene and the disease.
tumor (22 papers, 2012 to 2025). "Future research should focus on examining the interactions between SPC25 and various immune cell types within the tumor immune microenvironment, such as tumor-associated macrophages, T cells, and dendritic cells." (PMID 40400636, 2025). "SPC25 overexpression has been associated with more aggressive tumor phenotypes, including larger tumor size, increased lymphatic invasion, and higher rates of metastasis." (PMID 40400636, 2025). "Elevated SPC25 levels are frequently associated with advanced tumor stages, higher rates of metastasis, and poor OS in cancer patients." (PMID 40400636, 2025). "We therefore investigated the relationship between SPC25 expression and mutation frequencies in these tumor-related genes in BC." (PMID 31400751, 2019). "In addition to promoting cell proliferation, SPC25 has been implicated in enhancing cancer cell migration and invasion, two key processes involved in tumor metastasis." (PMID 40400636, 2025). "Furthermore, GSEA enrichment findings revealed that SPC25 exhibited a strong association with immune and inflammatory responses, protein metabolism, spindle filament activity, and chromosome activity, aligning with established tumor mechanisms." (PMID 38605119, 2024). "Experiments in cancer cells and animal models confirmed that SPC25 is a key driver of tumor growth; turning it off significantly slowed cancer progression." (PMID 41375045, 2025). "Single-cell sequencing revealed high SPC25 expression in tumor cells and specific immunosuppressive T-cell subsets." (PMID 41375045, 2025). "Elevated SPC25 expression has been linked to poor prognosis and aggressive features in CRC, including advanced tumor stage and distant metastasis." (PMID 40400636, 2025). "Many of the studies to date have focused on the correlation between SPC25 expression and tumor progression, but the specific signaling pathways or molecular interactions through which SPC25 exerts its oncogenic effects are not fully understood." (PMID 40400636, 2025). "Additionally, SPC25 overexpression may be linked to tumor evolution and resistance to treatment." (PMID 40400636, 2025). "At present, SPC25 has been shown to predict the efficacy of tumor immunotherapy, but the research on SPC25 inhibitors combined with immunotherapy is limited." (PMID 40400636, 2025). "Critically, in vivo xenograft experiments demonstrated that SPC25 depletion markedly suppressed tumor growth." (PMID 41375045, 2025). "This suggests that SPC25 contributes to GC progression by promoting tumor cell proliferation and migration through its involvement in cell cycle regulation and mitotic progression." (PMID 40400636, 2025). "Several preclinical studies have demonstrated the effectiveness of RNAi-mediated knockdown of SPC25 in inhibiting cancer cell proliferation and reducing tumor growth." (PMID 40400636, 2025). "Functional assays demonstrated that SPC25 depletion significantly impaired tumor cell proliferation (EdU assay), clonogenicity (colony formation assay), and migration (wound healing assay)." (PMID 41375045, 2025). "Single-cell sequencing analysis revealed that SPC25 is predominantly highly expressed in tumor cells and specific immunosuppressive cell populations, such as CD8-depleted T cells and Tregs." (PMID 41375045, 2025). "Studies have demonstrated that SPC25 is upregulated in tumor tissues compared to adjacent normal tissues, and its expression often correlates with aggressive tumor features, such as larger tumor size and lymph node involvement." (PMID 40400636, 2025). "The findings revealed a substantial upregulation of SPC25 expression in the platinum‐resistant clinical tumor tissue samples, corroborating our earlier preclinical observations." (PMID 39488790, 2024). "Preliminary in vitro and in vivo functional tests of tumor cells have corroborated that elevated SPC25 expression can stimulate HCC cell proliferation and augment cancer stem cell (CSC) characteristics." (PMID 38605119, 2024).
tumor (continued). "In our further experimental investigations, we have downregulated the expression of SPC25 and observed a significant inhibition of glucose uptake and lactate production in tumor cells." (PMID 38217547, 2024). "In our investigation, we meticulously examined SPC25 expression across various cancer types, encompassing analyses of differentially expressed genes (DEGs), prognosis, and enrichment across diverse tumor classifications." (PMID 38605119, 2024). "Further analysis revealed that SPC25 expression significantly increases the abundance of tumor‐initiating cells (TICs) within tumors, whereas its suppression reduces it considerably." (PMID 39488790, 2024). "Materials and Methods: The differential expression of SPC25 in tumor samples and normal samples was analyzed using TIMER, TCGA, GEO databases, and the correlation between its expression and clinicopathological features and prognosis in LUAD patients." (PMID 38217547, 2024). "Whereas, there are few studies concentrated on the relationship of SPC25 with tumor cell proliferation and energy metabolism in LUAD." (PMID 38217547, 2024). "Compared to existing research, our study provides in-depth research on the role of SPC25 in tumor cell energy metabolism and uncovers potential connections with glycolysis-related genes." (PMID 38217547, 2024). "We further validated the tumor‐initiating ability of SPC25 in vivo through limiting dilution assays in BALB/c‐Nude mice." (PMID 39488790, 2024). "As a critical component of the NDC 80 complex, the induction of disorganized cell mitosis by SPC25 overexpression leads to enhanced proliferative capacity and deepening of malignancy in tumor cells and further worsens the prognosis of patients with tumors." (PMID 37059592, 2023). "SPC25 was significantly up-regulated in tumor tissue, and can independently predict the prognosis of patients." (PMID 36052378, 2022). "In conclusion, we finally identified five genes most associated with tumor progression and prognosis: VRK1, NUP37, HMMR, SPC25, and RUVBL1." (PMID 36052378, 2022). "The correlation analysis also suggested that high SPC25 expression was correlated with unfavorable clinical parameters, including poor tumor differentiation, advanced TNM stage, and HBV infection." (PMID 36147467, 2022). "High expression of SPC25 as a key component of the NDC80 complex leads to enhanced tumor cell proliferation and advanced degree of malignancy by inducing disorganized cell mitosis, further affecting the prognosis of patients with tumors." (PMID 36147467, 2022). "The NDC80 complex, including the main elements of NDC80, SPC24, and SPC25, is highly expressed in various tumors and cooperatively promotes the invasion and metastasis of tumor cells." (PMID 33778011, 2021). "The results from the correlation analyses demonstrated that a total of 3 kinds of tumor-infiltrating immune cells were correlated with the expression of SPC25." (PMID 32742802, 2020). "The average mRNA level of SPC25 in HCC was significantly higher when compared with that in the non-tumor tissue (4.12 vs. 1, respectively, P < 0.0001, paired student's t-test)." (PMID 33408271, 2020). "Both in vitro and in vivo assays showed that overexpression of SPC25 significantly promotes HCC tumor growth." (PMID 33408271, 2020). "Functional studies demonstrate that SPC25 enhances both in vitro and in vivo tumor growth of HCC by accelerating the cell cycle." (PMID 33408271, 2020). "Elevated SPC25 mRNA levels (defined as a two-fold increase) were detected in 72/105 (68.6%) of HCC tissues compared to matched non-tumor tissue." (PMID 33408271, 2020). "Increased SPC25 protein levels were detected in 151/223 (67.7%) of informative LIHC tissues compared with adjacent non-tumor tissue." (PMID 33408271, 2020). "Recent literature reported that overexpression of SPC25 was related to poor prognosis of HCC via promoting tumor growth and metastasis." (PMID 33408271, 2020).
tumor (continued). "Among them, activated CD4 T memory cells were positively correlated with SPC25 expression; two kinds of tumor-infiltrating immune cells were negatively correlated with SPC25 expression, including regulatory T cells (Tregs), and resting memory CD4 + T cells." (PMID 32742802, 2020). "SPC25 expression, which was present in most human tissues, was significantly higher in BC tumor tissues than that in corresponding normal tissues." (PMID 31400751, 2019). "Compared to SPC25- cells, SPC25+ cells formed significantly more tumor spheres in culture, appeared to be more resistant towards docetaxel-induced cell apoptosis, and generated larger tumors with higher frequency after serial adoptive transplantation." (PMID 30408771, 2018). "A total of 3 rounds of serial adoptive transplantations were performed, showing more frequent tumor formation in SPC25+ cell-transplanted mice, compared to SPC25- cell-transplanted mice." (PMID 30408771, 2018). "Firstly, tumor sphere formation was tested, showing that significantly more tumor spheres were formed in SPC25+ cells, compared to SPC25- cells, shown by representative images, and by quantification." (PMID 30408771, 2018). "These inhibitors could be tested in preclinical models to assess their ability to disrupt SPC25 function and inhibit tumor growth." (PMID 40400636, 2025). "These pathways, which are frequently dysregulated in cancer, could lead to the overexpression of SPC25, contributing to tumor progression." (PMID 40400636, 2025). "The tumor immune microenvironment plays a crucial role in cancer progression and response to treatment, and recent studies suggest that SPC25 may influence immune cell function and immune evasion mechanisms." (PMID 40400636, 2025). "Liquid biopsy assays targeting SPC25 could provide a real-time snapshot of tumor dynamics, enabling more personalized and timely treatment decisions." (PMID 40400636, 2025). "Moreover, the role of SPC25 in modulating the tumor microenvironment (TME) and its crosstalk with other cellular pathways have further expanded its relevance in cancer biology." (PMID 40400636, 2025). "In addition to its involvement in tumor progression, SPC25 plays a critical role in cancer cell resistance to chemotherapy and targeted therapies." (PMID 40400636, 2025). "However, further research is still needed to explore the interaction network between SPC25 and glycolysis-related genes, as well as the specific regulatory mechanisms of these genes in tumor occurrence and development." (PMID 38217547, 2024). "In conclusion, SPC25 may have a significant relationship with tumor immune regulation, so we further explored the role of SPC25 at the gene level." (PMID 38605119, 2024). "Moreover, we noted a marked positive correlation between SPC25 expression and tumor purity–corrected mRNAsi." (PMID 39488790, 2024). "This suggests that SPC25 plays a pivotal regulatory role in tumor cell energy metabolism." (PMID 38217547, 2024). "A positive feedback loop comprising SPC25 and β‐catenin may also exist in EOC cells; it illustrates the intricacies of Wnt pathway signal transduction in tumor cells and highlights SPC25 as a central target within the positive feedback circuitry." (PMID 39488790, 2024). "Finally, the relationship between SPC25 and immunotherapy response was further explored through Gene Set Enrichment Analysis, tumor microenvironment, and immune cell infiltration." (PMID 38605119, 2024). "Furthermore, we have validated the crucial role of SPC25 in glucose uptake and lactate production in tumor cells through cellular experiments." (PMID 38217547, 2024). "Some progress has also been made in the study of spindle component 25 (SPC25) in tumor progression." (PMID 32322168, 2020).
tumor (continued). "The combined detection of NDC80, NUF2, SPC24 and SPC25 may become a new research direction in tumor diagnosis and a new target for tumor targeted gene therapy." (PMID 32226507, 2020). "Moreover, the up-regulation of SPC25 was observed in lung cancer, prostate cancer, and breast cancer, significantly enhancing the proliferation of these tumor cells." (PMID 33408271, 2020). "SPC25 might also serve as a biomarker for evaluating the status of the tumor microenvironment and as an immunotherapy target in BC patients." (PMID 31400751, 2019). "Serial adoptive transplantation of SPC25+ and SPC25- cells to form tumor was also assessed." (PMID 30408771, 2018). "Thus, SPC25 may play a crucial role in promoting stemness in tumor cells, potentially contributing to resistance to platinum‐based chemotherapy." (PMID 39488790, 2024). "Several studies on in vitro and in vivo functional assays of tumor cells preliminarily verified that the high SPC25 expression can promote cell proliferation in HCC and enhanced CSC properties; however, the regulatory mechanisms underlying this process remain unclear." (PMID 36147467, 2022). "Spindle component 25 (SPC25) is a key component of the nuclear division cycle 80 (NDC80) complex, and its high expression promotes tumor cell proliferation by inducing mitotic disorder." (PMID 40454580, 2025). "We begin by exploring the structural and functional characteristics of SPC25 within the NDC80 complex, followed by its dysregulation in different tumor types and its impact on tumor progression." (PMID 40400636, 2025). "In contrast, SPC25 silencing in OVCAR8 cells led to an increase in CDDP sensitivity and apoptotic index, as well as prolonged survival, in the tumor‐bearing mice." (PMID 39488790, 2024). "Our results uncovered a robust correlation between SPC25 and the infiltration of diverse immune cell types (such as CD4 + T cells, macrophages, and T cell regulation) within multiple tumor TMEs." (PMID 38605119, 2024). "We also found that interfering with the expression of SPC25 can significantly inhibit the proliferation and migration of LUAD cells, and promote the apoptosis of tumor cells." (PMID 38217547, 2024). "In tumor tissues, CCNB2, DYNC1LI1, SPC25 and KIF18A expressions were mainly detected in the cytoplasm, and KIF11 expression was detected mainly in the cytoplasm and nucleus." (PMID 33111935, 2020). "SPC25 promoted HCC cell proliferation in vitro and tumor growth in vivo by accelerating the cell cycle." (PMID 33408271, 2020). "NDC80 and SPC25 expression, TNM grade, tumor status, residual tumors, radiotherapy were used to construct a nomogram for risk assessment." (PMID 32226507, 2020). "It is therefore possible that SPC25 is a downstream target of CCL7 and is partially responsible for CCL7-induced promotion of tumor cell proliferation." (PMID 31400751, 2019). "Same number of SPC25- or SPC25+ PrC cells from both DU145 and LNCap lines were subcutaneously transplanted into nude mice and assess for the tumor formation by bioluminescence after 8 weeks." (PMID 30408771, 2018). "Additionally, the expression levels of tumor/normal ratios of CDCA1, KNTC2, SPC24 and SPC25 correlated with each other in CRCs, and the cell growths after the small interfering RNA (siRNA)-mediated knockdown were significantly suppressed." (PMID 40400636, 2025). "Therefore, further investigation of the effect of SPC25 on LUAD, particularly through modulating tumor cell glycolysis, ferroptosis, and ceRNA biological functions, plays a crucial role in improving diagnosis and treatment of LUAD patients." (PMID 38217547, 2024). "Taken together, we could draw a deduction that DNA-PK, AKT, and Notch1 signaling pathways might be the critical mechanism that promoted the tumor growth and progression in HCC cells with SPC25 upregulation." (PMID 36147467, 2022).
tumor (continued). "The combined detection of NDC80, NUF2, SPC24 and SPC25 may become a new research direction in LUAD diagnosis and a new target for tumor targeted gene therapy." (PMID 32226507, 2020). "In this study, it was found that NDC80, NUF2, SPC24 and SPC25 genes were differentially expressed in tumor tissues and normal tissues and NDC80, NUF2, SPC24 and SPC25genes have diagnostic values for LUAD." (PMID 32226507, 2020). "Furthermore, exploring how SPC25 modulates the TME, including interactions with stromal cells, immune cells, and EMC components, will provide valuable insights into its broader role in tumor progression and metastasis." (PMID 40400636, 2025). "SPC25 functions as an oncogene related to the regulation of tumor cell stemness to promote HCC progression via the DNA-PK/AKT/Notch1 pathways whose detailed relationships remain to be determined and blockade of these pathways suppressed the tumorigenic effect induced by SPC25 upregulation." (PMID 36147467, 2022). "Consequently, we surmise that SPC25 may modulate immune cells in the tumor microenvironment via numerous pathways, as opposed to exclusively targeting specific immune cells." (PMID 38605119, 2024). "Importantly, SPC25 showed a significant positive correlation with COAD expressing many immune checkpoint genes, especially NRP1, CD276, TNFSF14, and other important immunotherapeutic targets, which may also be closely related to the immune escape mechanism of ACC tumor cells." (PMID 38605119, 2024).